BRD1 (bromodomain containing 1)
Diseases named in the same sentence as BRD1 in open-access papers (continued):
Sharing a sentence is not in itself a finding about the gene and the disease.
cancer (13 papers, 2012 to 2025). A tumor composed of atypical neoplastic, often pleomorphic cells that invade other tissues. "In our study, higher mRNA and protein expressions of BRD1 were found in HCC tissues, and mRNA expression of BRD1 was remarkably linked with cancer stages and tumor grades." (PMID 32927435, 2020). "Our study demonstrated that increased expressions of BRD1/2/3/4/7/8/9 were found to be significantly correlated with clinical cancer stages and pathological tumor grades in HCC patients." (PMID 32927435, 2020). "BRD1/2/3/4/7/8/9 were over-expressed in HCC and were significantly associated with clinical cancer stages and pathological tumor grades." (PMID 32927435, 2020). "Results from our study demonstrated that over-expressions of mRNA and protein were found in BRD1/2/3/4/7/8/9, and mRNA expressions of these genes were significantly correlated with cancer stages and tumor grades in HCC patients." (PMID 32927435, 2020). "Among the recurrent genomic events, those in BRD9, EP300, ATAD2, HDAC4, PRBM1, BRD4, and BRD1 were observed in the highest numbers of cancer types (nine, eight, eight, eight, seven, seven, and seven, respectively)." (PMID 30760718, 2019). "These included several cancer-associated genes such as MKL1, EP300, NF2, and HIC2 and chromatin binding genes BRD1, HIRA, and HDAC10." (PMID 25909290, 2015). "We hypothesize that the effects of BRD1 on cancer progression might be modulated through interactions with other molecules, which can obscure its direct impact on patient outcomes." (PMID 39962068, 2025). "Conversely, perturbations that may promote aberrant stem cell-like activity and impair differentiation (cancer-promoting genes) included bromodomain-containing proteins (BRD1, BRD2), histone acetyltransferases (EP300), and histone lysine methyltransferases (KMT2C, NSD1, SETD1B)." (PMID 38472198, 2024). "BRD1, BRD2, BRD3, BRD4, and BRD7-9 were significantly upregulated in tumor samples expressing high levels of p16, a surrogate biomarker for HPV-positive cancers, and the presence of HPV DNA through in situ hybridization, compared to normal samples (p<0.05)." (PMID 39301555, 2024). "The transcriptional levels of BET (BRD1,BRD2,BRD3, BRD4 and BRDT) were compared between cancer and normal samples in GEPIA database." (PMID 36711038, 2023). "Taken together, these results indicated that the mRNA levels of BRD1/2/3/4/7/8/9 were commonly up-regulated in HCC and correlated with cancer stages and histological grades in HCC patients." (PMID 32927435, 2020). "For example, 66.7% (42/63) of putative therapeutic target HAMPs are largely uncharacterized with limited indications about how these genes influence cell biology and cancer, although many of these understudied HAMPs are recurrently altered among cancers, such as BRD9, BRD1, BPTF, and ATAD2." (PMID 30760718, 2019).
tumor (7 papers, 2012 to 2025). "To further validate the oncogenic effect of BRD1 in vivo, we conducted experiments that demonstrated a significant reduction in tumor volumes and weights upon BRD1 knockdown, indicating effective tumor regression." (PMID 39962068, 2025). "In this study, we demonstrated that knocking down BRD1 expression led to a reduction in cell proliferation, metastasis, and tumor growth, both in vitro and in vivo." (PMID 39962068, 2025). "Despite these advancements, the precise function of BRD1 that bridges its molecular mechanisms with tumor-related pathologies remains largely unexplored." (PMID 39962068, 2025). "Thus, BRD1 likely functions as an integral component within a broader network of genes and proteins, each playing distinct roles at different stages of tumor progression." (PMID 39962068, 2025). "Moreover, the result of immunohistochemical (IHC) staining also revealed a marked decrease in PCNA protein levels in tumor tissue following BRD1 inhibition." (PMID 39962068, 2025). "Furthermore, downregulation or inhibition of BRD1 may enhance anti-tumor immune function by negatively regulating the activation states of T cells and natural killer (NK) cells." (PMID 39962068, 2025). "Moreover, BRD1 was significantly increased in patients with a more advanced tumor grade, especially grade 3, suggesting that BRD1 expression was significantly correlated with high-grade 3 tumor." (PMID 39962068, 2025). "Nonetheless, despite successfully inhibiting BRD1, we observed a concurrent downregulation of SREBF1, FASN and SCD1 within the HCC tumor tissue." (PMID 39962068, 2025). "Bromodomain proteins, such as BRD1 and BRD4, play a role in the development of immune and hematological cells and in the regulation of tumor inflammation." (PMID 35634343, 2022).
neurodevelopmental disorder (2 papers, 2023 to 2026). A behavioral and cognitive disorder with onset during the developmental period that involves impaired or aberrant development of intellectual, motor, or social functions. "Our findings highlight BRD1 as a key regulator of neurodevelopmental timing and synaptic maturation, and network activity reinforcing growing evidence that disruptions in chromatin-mediated control of differentiation and synaptic organization contribute to neurodevelopmental disorders." (PMID 41756449, 2026).
BRD1 also shares sentences with these, for which no sentence is quoted: autism (2 papers); Anxiety (1); infection (1); liver cancer (1); lung carcinoma (1); mental retardation (1); ovarian carcinoma (1); rheumatoid arthritis (1).